EGFR (epidermal growth factor receptor)
Diseases named in the same sentence as EGFR in open-access papers (continued):
Sharing a sentence is not in itself a finding about the gene and the disease.
lung cancer (continued). "With this background, this study sought to evaluate the clinical performance of the RT-PCR and MS tests in the setting of everyday testing of tumour specimens from lung cancer patients for EGFR gene mutations." (PMID 29254176, 2017). "Mutations in the epidermal growth factor receptor gene (EGFR) are found in 10–15% of lung cancers in Caucasians, and 30–40% of East Asian patients." (PMID 28620581, 2017). "When cocultured with EGFR mutation positive lung cancer cells, these CAFs increased the apoptic effect of gefitinib on cancer cells, whereas, in the absence of gefitinib, they did not affect cancer cell viability." (PMID 28429795, 2017). "From these results, we propose that RHOB levels can predict resistance to EGFR‐TKI in lung cancer tumors harboring an EGFR mutation." (PMID 28003335, 2017). "The epidermal growth factor receptor (EGFR) mutation is one of the most prevalent genetic alterations in lung cancer patients." (PMID 29228697, 2017). "Gefitinib showed response in phase II clinical trials and with better clinical response in lung cancer with activating mutations in the tyrosine kinase domain of the EGFR." (PMID 29069801, 2017). "Further, acquired resistance to osimertinib is associated with RAS signaling in lung cancer cells harboring activating EGFR mutations with EGFR T790M as well as the appearance of cancer cells harboring EGFR T790M with wild-type EGFR in refractory tumors." (PMID 29050315, 2017). "We here determined the frequency of T790M acquisition at diagnosis of progressive disease in patients with EGFR-mutated non–small cell lung cancer (NSCLC) treated with afatinib as first-line EGFR-TKI." (PMID 28978102, 2017). "A total of 102 patients with EGFR-mutated lung cancer were enrolled, 53 had available plasma samples at disease progression, and 28 underwent serial plasma sampling during EGFR-TKI treatment." (PMID 29029416, 2017). "We recommend that all lung cancer MDTs review their local EGFR mutation testing practice to ensure robust systems are in place and patients are given every opportunity to receive optimum treatment." (PMID 28367333, 2017). "Patients with lung cancer usually acquire resistance to EGFR TKIs due to the T790M mutation, the secondary mutation in EGFR." (PMID 27713133, 2017). "The development of tyrosine kinase inhibitors (TKIs) to epidermal growth factor receptor (EGFR) mutated NSCLC heralded the era of precision medicine in lung cancer." (PMID 28443282, 2017). "In conclusion, we generated lung cancer cell lines harboring an EGFR T790M mutation with a CRISPR/Cas9-based approach." (PMID 28422737, 2017). "Impact of EGFR activating mutation on survival of non-small-cell lung cancer patients by family history of lung cancer: Multivariate analysis results." (PMID 28486527, 2017). "The identification of epidermal growth factor receptor (EGFR) mutations in NSCLC and the association between EGFR mutations and gefitinib sensitivity have changed the way lung cancer is diagnosed and treated." (PMID 29110716, 2017). "EGFR mutations are present in around 7% of lung adenocarcinoma cases in the western world, and in 30% of lung cancer cases in the Far East." (PMID 29029422, 2017). "In particular, gene sets related to KRAS, EGFR, mir-let7a3 were found to be significantly associated with lung cancer survival." (PMID 28697753, 2017). "Several phase III studies have confirmed that patients with advanced lung cancer and EGFR mutations benefit more from first-line targeted EGFR-TKI therapies, such as gefitinib and erlotinib, than from the standard platinum doublet chemotherapy." (PMID 29228636, 2017). "Here we established two sublines (BR1-8 and BR2-3) resistant to a second-generation inhibitor, afatinib, from the human lung cancer cell line HCC827 that harbors a mutation that activates the tyrosine kinase activity of EGFR." (PMID 29050315, 2017). "Specifically, the discovery of epidermal growth factor receptor (EGFR) mutations has changed lung cancer treatment." (PMID 28949965, 2017).
lung cancer (continued). "The most common EGFR mutation leading to resistance is T790M, which accounts for 50% of EGFR-mutant lung cancers with acquired resistance." (PMID 28915640, 2017). "In a second study, higher phospho-MARCKS staining was associated with shorter survival in a series of 195 operated lung cancers and associated with EGFR-TKI-based treatment in a series of 52 treated metastatic patients." (PMID 28009981, 2017). "H1975 lung cancer cells with EGFR T790M mutations that confer resistance to EGFR inhibitors underwent prolonged treatment with the PI3K/mTOR inhibitor, BEZ235." (PMID 29299135, 2017). "The mutated epidermal growth factor receptor (EGFR) gene is an important driver gene in lung adenocarcinoma, and plays an important role in the development of lung cancer." (PMID 28532538, 2017). "Though harbored by only 4–6% of lung adenocarcinomas, EML4-ALK fusion has been recognized as the second most important event to consider in the targeted treatment of lung cancer, following the EGFR mutation." (PMID 28535796, 2017). "Combination therapy of erlotinib plus bevacizumab improves progression-free survival of patients with epidermal growth factor receptor–mutated (EGFR-mutated) advanced non–small-cell lung cancer (NSCLC) compared with erlotinib alone." (PMID 29196706, 2017). "In this study, we showed that the triplet therapy, which included afatinib, cetuximab, and bevacizumab, induced pathological complete remission (CR) repeatedly in lung cancer cells harboring EGFR T790M mutations in vivo." (PMID 28388009, 2017). "Currently, epidermal growth factor receptor (EGFR) mutation is the most common type of gene mutations detected in Asian populations with lung cancer, which mainly includes exon 21 L858R point mutation and exon 19 deletion (19 del) mutation." (PMID 28396596, 2017). "EGFR-TKIs have been shown to have significant clinical therapeutic effects in patients with lung cancer who harbor EGFR activating mutations." (PMID 29121075, 2017). "We completely recognize the importance of testing our nanoparticles in lung cancer cell lines with EGFR mutations and will do that in the future if possible." (PMID 28854941, 2017). "Patients with EGFR mutant lung cancers with the T790M mutation were enrolled in a trial of rociletinib, a third generation inhibitor that targets T790M-mutant EGFR." (PMID 28431544, 2017). "Germ-line mutations of EGFR gene such as T790M or V843I can begin to explain familial aggregation of lung cancer patients; its presence is important in developing resistance to EGFR-TKIs." (PMID 28486527, 2017). "MiR-218 has been reported to target EGFR, an important kinase implicated in signaling in lung cancer cells." (PMID 28830450, 2017). "First and second generation EGFR inhibitors, erlotinib, gefitinib and afatinib, have now established role in the treatment of patients with lung carcinomas harboring activating EGFR mutations." (PMID 27924059, 2017). "The pro-tumorigenic mechanism of LL-37 appears to involve the activation of EGFR, a tyrosine kinase receptor widely implicated in lung cancer development." (PMID 26395996, 2016). "A different sensitivity to EGFR TKIs is also present between lung cancer patients with common and uncommon mutations." (PMID 27433281, 2016). "The systematic analysis of gene profiles affected by TOPK and c-Jun will provide a clear depiction of the integrated regulatory network underlying lung cancer resistance to EGFR-TKIs." (PMID 26745678, 2016). "In particular, the existence of mutations in the ICD of EGFR that causes a constitutive or ligand-independent EGFR signaling activation has been widely studied in lung cancer and glioblastoma." (PMID 27104520, 2016). "In this report, we describe cases of lung cancer with concurrent EGFR mutation and ALK rearrangement and identify their clinical characteristics." (PMID 27026837, 2016).
lung cancer (continued). "Within each lung cancer patient with the mutant T790M allele, comparison of the distribution of the EGFR WT allele and the mutant T790M allele fragment lengths identified a general trend for the mutant allele to occur more commonly at shorter fragment lengths." (PMID 27428049, 2016). "In the present study, each lung cancer family in Cohort-2 consisted of at least two members with this disease and all of them had available tissue for EGFR mutation analysis." (PMID 27449093, 2016). "We further confirmed the sensitivity of EGFR mutation-positive lung cancer cell lines derived from patients to HC (hyperthermic chemotherapy) treatment." (PMID 26654941, 2016). "EGFR is involved in cell proliferation and motility and its over-expression has been found to be implicated in various cancers including lung cancer." (PMID 26820293, 2016). "Circulating tumor DNA (ctDNA) is an approved noninvasive biomarker to test for the presence of EGFR mutations at diagnosis or recurrence of lung cancer." (PMID 28027313, 2016). "A propensity score with 1:2 matching (n = 248) was conducted to estimate the chance of specific EGFR mutation types among EGFR-mutant lung adenocarcinoma patients with family history of lung cancer." (PMID 27449093, 2016). "The use of specific tyrosine kinases inhibitors overturned the biological behaviour of EGFR mutation positive tumours and became a preclinical model to understand the heterogeneity of lung cancers and the mechanisms of drug resistance." (PMID 27433281, 2016). "Establishing the KRAS mutational status of tumor samples is essential to manage patients with colorectal or lung cancer, since these mutations preclude treatment with monoclonal anti-epidermal growth factor receptor (EGFR) antibodies." (PMID 27632281, 2016). "For example, the widely used FDA-approved cobas® EGFR Mutation Test only detects exon 19 deletion and L858R mutations, which together only comprise the mutations found in 85% of EGFR-mutated lung cancers." (PMID 27043212, 2016). "The epidermal growth factor receptor (EGFR) mutation status assessment has become increasingly important given the significant impact of tyrosine kinase inhibitors in lung cancer management." (PMID 27215400, 2016). "AXL activation has been recently reported to confer acquired resistance to EGFR-TKIs in lung cancers with EGFR mutations." (PMID 27100677, 2016). "Since KRAS mutations were frequently evaluated alongside EGFR in cases of lung cancers at our institution, we also wanted to compare the performance of both methods on this gene." (PMID 27043212, 2016). "Despite being the basis of one of the most effective interventions in lung cancer, little is known about the patterns of epidermal growth factor receptor (EGFR) mutation testing in the general population." (PMID 27294665, 2016). "This study was designed to broaden our understanding of the molecular mechanisms of acquired resistance to erlotinib in lung cancer cells bearing wild type or mutated EGFR." (PMID 27248176, 2016). "Upregulation of CNV of the cancer related genes, such as Myc, EGFR, ErbB, was associated with the lung cancer." (PMID 26663100, 2016). "Epidermal growth factor receptor (EGFR) mutation is the most common oncogenic driver in East Asians with lung cancer." (PMID 27384480, 2016). "Previous studies have shown that EGFR polymorphisms are associated with patient prognosis in a variety of cancers such as head and neck cancer, lung cancer, colorectal carcinoma, breast cancer, bladder cancer and esophageal cancer." (PMID 27437777, 2016). "In conclusion, this study provides a comprehensive report of lung cancer EGFR mutation detection from platform establishment, method validation to clinical routine practice." (PMID 27480787, 2016).
lung cancer (continued). "As the genetic similarity is supposed to be much higher among first-degree relatives, the major objective of this study was to evaluate the possible link between the presentation of EGFR mutations and a family history of lung cancer." (PMID 27449093, 2016). "In our study, a higher expression of CDH5 was also observed in PC9 lung cancer cells with exon 19 deletion mutation and lung cancer cells transfected with exon 19 deletion mutant EGFR gene." (PMID 27362942, 2016). "In this study, we studied the association of CDH5 expression with common EGFR mutations (exon 19 delE746-A750 and exon 21 L858R) in lung cancer cells and mouse xenograft models." (PMID 27362942, 2016). "The standard molecular testing for lung cancer is to check for mutations of two molecules: epidermal growth factor receptor (EGFR) and rearrangement of anaplastic lymphoma kinase (ALK)." (PMID 26944944, 2016). "Although previous studies have shown a positive association between family history of lung cancer and EGFR mutation prevalence, the EGFR mutation subtype spectrum among lung cancer families has not been investigated yet." (PMID 27449093, 2016). "The lung cancer EGFR mutation status was L858R and wild type, probably because of heterogeneity among tumor nodules." (PMID 27900359, 2016). "The SNP EGFR-N158N has previously been associated with a higher risk of developing head and neck cancer, but its role in the development of lung cancer is unclear." (PMID 27776352, 2016). "In the unadjusted model of unconditional logistic regression analysis (n = 1713), there was a significant association between family history of lung cancer and EGFR mutation rate (Odds ratio 1.47, 95% CI 1.01–2.14, P = 0.042)." (PMID 27449093, 2016). "We compared lung cancer patients receiving EGFR-TKI treatment with high-risk healthy volunteers who are smokers with more than 20 pack-years." (PMID 27186495, 2016). "In our study, we also observed that the increased expression of CDH5 was associated with EGFR mutations in lung cancer cells." (PMID 27362942, 2016). "As such, our findings that ZEB1 distinctly regulates (promotes or suppresses) the growth of lung cancer cells harbouring KRAS or EGFR mutations is an important new observation." (PMID 27456471, 2016). "Similar to the hematological malignancies, a loss of heterozygosity of c-Cbl was noted in lung cancer and its combinatorial effect with other mutations such as EGFR or Met was proposed as a mechanism of tumorigenesis." (PMID 27661103, 2016). "Our work illustrates that IPHC-CT should be recommended for EGFR mutation positive lung cancer patients." (PMID 26654941, 2016). "Although both MET gene amplification and HGF treatment has been shown to induce gefitinib resistance in lung cancers with EGFR mutations, ErbB3 transactivation is involved only in MET amplification but not in HGF-induced resistance." (PMID 26919104, 2016). "After adjusting for propensity and all variables, lung cancer family history remained a significant predictor of EGFR mutations (Odd ratio 1.83, 95% CI 1.19–2.84, P = 0.006 and 1.68, 95% CI 1.06–2.67, P = 0.028, respectively)." (PMID 27449093, 2016). "The guideline suggests that lung cancer tissues are tested by PCR for EGFR mutations and by FISH for ALK mutations." (PMID 27448564, 2016). "These drugs are particularly effective in lung cancers with activating EGFR mutations such as exon 19 deletion and exon 21 L858R mutation." (PMID 27270313, 2016). "The main objective of this nationwide study was to investigate the characteristics of young adult lung cancer in Taiwan, especially the relationships among smoking behavior, EGFR mutation, and age." (PMID 27191886, 2016). "Multiple studies of treatment-naive EGFR-mutated lung cancer have since shown that EGFR TKIs outperform chemotherapy in terms of PFS and response rate." (PMID 29152393, 2016).
lung cancer (continued). "Within lung cancer, current investigations include the evaluation of EGFR mutations identified in ctDNA, and observing tumor response and tumor resistance to EGFR treatments using next-generation sequencing to track ctDNA changes." (PMID 27367729, 2016). "Our work therefore showed IPHC-CT is an effective treatment for EGFR kinase domain mutation positive lung cancer patients." (PMID 26654941, 2016). "Compared to wild type EGFR gene transfected cells, increased expressions of phospho-EGFR (Y1068) and phospho-Akt proteins were detected in exon 19 E746-A750 deletion mutation EGFR gene transfected A549 lung cancer stable cells." (PMID 27362942, 2016). "All these results suggested that family history of lung cancer is independently associated with a higher EGFR mutation rate." (PMID 27449093, 2016). "To date, only a few small-scale studies have analyzed the mutation status of EGFR and K-ras in both primary and metastatic sites of lung cancer." (PMID 27070580, 2016). "A study revealed that HGF activated the MET-ERK pathway, inducing resistance to erlotinib in an EGFR-mutated lung cancer cell line, KHM-3S, and the sensitivity of erlotinib was restored by crizotinib." (PMID 27331411, 2016). "Epidermal growth factor receptor mutations (mEGFR) and kirsten rat sarcoma viral oncogene mutations (mKRAS) are the most common mutations in lung cancer." (PMID 27489355, 2016). "Despite the different mechanisms underlying cancer resistance to EGFR-TKIs and chemotherapy, these findings are in agreement with a recent report that miR-26a is among the key non-coding RNAs that mediate lung cancer resistance to cisplatin." (PMID 27285768, 2016). "Enhanced trans-activation of HER receptor activity appears to be a central event in receptor tyrosine kinase (RTK) activation by lung-cancer derived EGFR/HER mutations." (PMID 26689995, 2016). "Increased EGFR phosphorylation was observed in stable lung cancer cells with exon 19 deletion mutation in our study." (PMID 27362942, 2016). "We chose two human cancer cell lines with known mutations: EGFR mutations are found in 10–15 % of lung cancer patients." (PMID 27613601, 2016). "The main objective of this nationwide study was to investigate the characteristics of young lung cancer in Taiwan, especially the relationships among smoking behavior, epidermal growth factor receptor (EGFR) mutation, and age." (PMID 27191886, 2016). "We therefore suggest that IPHC-CT should be considered on lung cancer patients positive for EGFR kinase domain mutation." (PMID 26654941, 2016). "A significant portion of lung cancer patients harbor kinase domain mutations in the epidermal growth factor receptor (EGFR) which sensitizes lung cancer cells to EGFR tyrosine kinase inhibitors (TKI)." (PMID 26654941, 2016). "When activating mutations or deletions are responsible for EGFR hyperactivation, as is often is observed in lung cancer, TKIs are often initially effective treatment options." (PMID 27221039, 2016). "Current epidermal growth factor receptor (EGFR) tyrosine kinase inhibitors (TKIs) treatment, including gefitinib and afatinib, are highly effective to extracranial lung cancer patients with specific EGFR mutations." (PMID 27916828, 2016). "Among the patients negative for kinase domain mutations in our clinic, we notice that around 9.8% of wt-EGFR patients showing partial regression of lung cancer, and another 52% stable disease." (PMID 26646697, 2016). "The KRAS mutation has been used as a predictive marker of low sensitivity to EGFR-TKI in lung cancer cells harboring EGFR activating mutations." (PMID 26919104, 2016). "Previous study indicated that DDX3 overexpression facilitates generation of cancer stem cells (CSCs) in lung cancer cells harboring epidermal growth factor receptor (EGFR)-activating mutations." (PMID 27344963, 2016).